NFIA-AS2 (NFIA antisense RNA 2)
Gene: Long non-coding RNA gene on chromosome 1 (60,912,675 to 61,056,885, reverse strand). Ensembl gene ENSG00000237928.
Diseases named in the same sentence as NFIA-AS2 in open-access papers:
NFIA-AS2 is named in the same sentence as 1 disease in open-access papers, as found by Europe PMC text mining. Sharing a sentence is not in itself a finding about the gene and the disease. The quoted sentences say what the papers report.
Obesity (1 paper, 2023). Accumulation of substantial excess body fat. "NFIA-AS2 was found to be a nuclear localized long non-coding RNA expressed in tissues pertinent to human obesity." (PMID 36806387, 2023). "Of the obesity-related tissues we examined, NFIA-AS2 is highly expressed in brown preadipocytes." (PMID 36806387, 2023). "NFIA-AS2 is expressed in various human tissues that play a role in the development of obesity." (PMID 36806387, 2023).